ARID1A (AT-rich interaction domain 1A)
Diseases named in the same sentence as ARID1A in open-access papers (continued):
Sharing a sentence is not in itself a finding about the gene and the disease.
tumor (continued). "Proliferative tumours were characterized by high expression of the c-MET, ARID1A, CTNNB1, RAF1, LGR5, and GLUL1 genes." (PMID 36345011, 2022). "For cases with available panel sequencing of primary tumor tissue, the concordance with sequence variations in PDX tumors identified by RNAseq ranged between 75% (ARID1A) and 100% (VHL)." (PMID 35800063, 2022). "In tumors, knockout of ARID1A impaired transcriptional activation of SLC7A11 and makes tumor cells more sensitive to GSH metabolic pathway inhibitors due to insufficient cysteine supply." (PMID 36399105, 2022). "Virus-directed targeting of ARID1A coupled with small-molecule inhibition of the methyltransferase EZH2 leads to the synthetic lethal killing of both infected and uninfected tumour cells." (PMID 35393414, 2022). "In the 20 pairs of clinical samples we collected, rt-PCR results showed that ZNF678, ARID1A, XIAP, MIS18BP1, and MBTPS2 were highly expressed in tumor tissues." (PMID 36249009, 2022). "Bioinformatics analysis was performed to reveal variations in genes and signaling pathways, and ARID1A and PD-L1 expression and the number of PD1+ tumor-infiltrating lymphocytes (TILs) were measured by immunohistochemical staining." (PMID 35198440, 2022). "In the study by He and colleagues, ARID1A knockdown increased cell migration and invasion in vitro in MHCC-97H and Huh7 HCC cell lines and increased tumor growth in vivo in a xenografted HCC tumor model." (PMID 35669430, 2022). "The quantitative polymerase chain reaction (qPCR) analysis of ARID1A and E‐cadherin (CDH1) gene expression in patient COAD tumour samples revealed a positive relationship between the two genes regardless of tumour type." (PMID 36420658, 2022). "Based on tumor volume, PMN-MDSC neutralization reduced the growth of Arid1a KO cells to a level comparable to that of WT cells." (PMID 36435834, 2022). "In contrast, ARID1A overexpression rendered the tumors sensitive to anti-PD1 antibody treatment, as reflected by the further reduction in tumor volumes as compared to isotype treatment." (PMID 36435834, 2022). "Subsequent immunohistochemical staining confirmed that ARID1A expression was negatively correlated with PD-L1 expression and PD1+ TILs in the tumor microenvironment." (PMID 35198440, 2022). "Results from the TIMER database showed that the expression of ARID1A, ARID2, and ARID4A was positively related to tumor purity (p < 0.05), indicating that these three genes were lowly expressed in the HCC immune microenvironment." (PMID 36034939, 2022). "A second benefit of targeting ARID1A is the recent demonstration that inactivation of certain SWI/SNF chromatin remodelling complex subunits (i.e. ARID1A and PBRM1) renders tumours more likely to respond to ICIs32,46." (PMID 35393414, 2022). "Thus, in certain contexts, ARID1A might function in an oncogenic capacity to support tumour growth." (PMID 35167193, 2022). "Patient data showed an inverse correlation between ARID1A and TERT expression, indicating a putative tumor suppressor role for ARID1A in NB." (PMID 33404859, 2021). "The authors observed that depletion of ARID1A or ARID1B results in an increased rate of cell proliferation in the sympathoadrenal lineage, which ultimately leads to higher tumor penetrance." (PMID 33748136, 2021). "The expressions of ARID1A, ARID2, ARID3C, JARID1C and JARID2 were strongly correlated with tumour stage." (PMID 35127746, 2021).
tumor (continued). "Factors including gender, age, tumor size, histological grade, tumor location, TNM stage, ARID1A status, and CD47 expression were taken into multivariate survival analysis." (PMID 34805154, 2021). "ARID1A alteration in NSMP (NSMP_A) group correlates with high Ki67 proliferative index and with tumor recurrence." (PMID 33668727, 2021). "Herein, we focused on ARID1A, CSMD1, and SENP3 during tissue microarray analysis of 180 HCC samples paired with tumor and paracarcinoma tissues as a replication population." (PMID 33558447, 2021). "The IHC analysis of ARID1A, CSMD1, and SENP3 proteins showed that the expression level of all the three genes was significantly different between tumor and paracarcinoma tissues (P < 0.05)." (PMID 33558447, 2021). "The expression of ARID1A and ARID2 inhibited the proliferation and migration of LIHC cells and, thus, act as tumour suppressors." (PMID 35127746, 2021). "We found the co-occurrence of genetic mutations in tumors with PARP1 alterations to be involved with some genes such as KMT2D/2C as driver genes, PIK3CA, ARID1A, H3F3A, HIST3H3, RYR2, and thus, PARP1 alteration should promote tumor mutability." (PMID 34531868, 2021). "Mechanistically, ARID1A interacts with EZH2 via its C-terminal region and antagonizes EZH2-mediated IFN responsiveness, and the DUF3518 domain of ARID1A is essential for tumor cell IFN-γ response." (PMID 34671561, 2021). "ARID1A is a subunit of the SWI/SNF chromatin-remodeling complex encompassing multiple proteins including also ARID1B, SMARCA4, and SMARCB1 that have tumor-suppressor functions." (PMID 34737943, 2021). "This study indicates how the identification of ARID1A and β-catenin alterations in EC represents a simple and effective way to characterize NSMP tumor aggressiveness and metastatic potential." (PMID 33668727, 2021). "ARID1A, a key component of the SWI/SNF chromatin remodeling complex, was reported to act as a tumor suppressor in various cancers." (PMID 32824568, 2020). "A synthetic lethal relationship between ARID1A and EZH2 has been revealed in several tumor entities." (PMID 33344089, 2020). "By analysing the expression of five subunits of the SWI/SNF complex (INI1/SMARCB1, SMARCA2, SMARCA4, ARID1A, PBRM1), we further explored the relevance of alterations in chromatin remodelling in glandular differentiated tumours." (PMID 32198650, 2020).
tumor (continued). "The protein ARID1A is part of the SWI/SNF chromatin remodeling complex and is supposed to be a tumor suppressor." (PMID 32388637, 2020). "All cases (n = 30) with tumor tissue present in the TMA had retained H3K36me3 and ARID1A expression." (PMID 32103422, 2020). "ARID1A and PI3-Kinase (PI3K) pathway alterations are common in neoplasms originating from the uterine endometrium." (PMID 31391455, 2019). "(c) Glycerol gradients (10–30%) followed by SDS-PAGE analysis of rhabdoid tumor cell line G401, as compared to SMARCB1 wild-type cell line HA1E, show ARID1A is seen in higher fractions when SMARCB1 is expressed (left)." (PMID 30860482, 2019). "AT-rich interactive domain-containing protein 1A (ARID1A) is a subunit of the mammary SWI/SNF chromatin remodeling complex and a tumor suppressor protein." (PMID 31210753, 2019). "ARID1A, as a tumor suppressor, regulates CDKN1A and SMAD3 transcription and tumor growth by collaborating with p5344." (PMID 31772679, 2019). "Exceptions included events private to the primary tumor (SETD2 and ARID1A in LUAD6; NOTCH2 in SCLC1), or private to metastases (SMARCA4 in LUAD5; ARID1A in LUAD7)." (PMID 30348992, 2019). "Four of these genes (ARID1A, APC, CDKN2A, and ID3) showed significantly reduced protein expression in the majority of tumor samples, whereas the remaining four genes displayed changes only in a few tumors." (PMID 29109526, 2017). "The tumor suppressors PTEN and AT-rich interactive domain-containing protein 1A (ARID1A) were the only proteins that showed consistent expression changes between these shRNA-transfected groups using these arrays." (PMID 27980214, 2017). "ARID1A is required for SWI/SNF complexes to suppress DNA synthesis and as such ARID1A is considered a tumour suppressor since it regulates cell proliferation and functions to prevent genomic instability." (PMID 27920066, 2017). "miR-31 also regulates the expression of several target-suppressive or oncogenic genes, such as ARID1A, SATB2, EMSY, and ABCB9, to affect tumorigenesis and tumor progression and prognosis." (PMID 27793031, 2016). "The data presented here provide the pre-clinical and mechanistic rationale for assessing ARID1A defects as a biomarker of single-agent ATR inhibitor response and represents a novel synthetic lethalapproach to targeting tumour cells." (PMID 27958275, 2016). "Since ARID1A is a tumor suppressor, it was surprising that the mevalonate pathway was downregulated in OCCC when ARID1A was knocked out." (PMID 27654507, 2016). "A similar result was observed when ARID1A was suppressed, suggesting that PBRM1 and ARID1A are two potent tumor suppressors that inhibit the rate of tumor growth." (PMID 27764136, 2016). "The tumour suppressor genes ATM and ARID1A showed a disproportionately high percentage of nonsense or frameshift mutations." (PMID 27325016, 2016). "ARID1A function was evaluated in vitro in MHCC-97H and Huh7 HCC cell lines, and in vivo in a xenografted HCC tumor model." (PMID 25975202, 2015). "The mutation was often present in the metastatic tumor and absent from the primary tumor, indicating that ARID1A plays a more critical role in metastatic transformation." (PMID 40429787, 2025).
tumor (continued). "Our prior research has confirmed that ARID1A functions as the tumor suppressor of LUAD, and the absence of ARID1A activity has contributed to metastasis and resistance to first generation EGFR-TKI." (PMID 39773749, 2025). "The expression levels of ARID1A and miRNAs were investigated in 110 paired samples of tumor and adjacent non-tumor tissues of GC patients, as well as in 38 sectional normal gastric tissue samples." (PMID 39796161, 2025). "Quantitative analysis revealed statistically significant differences in ARID1A expression in tumor and non-tumor tissues compared to sectional gastric tissues of the healthy control group (p < 0.0001)." (PMID 39796161, 2025). "The Spearman’s correlation analysis revealed only weak negative relevance between ARID1A and miR-129-5p expression in tumor r = −0.2 (p = 0.04) and non-tumor tissues r = −0.18 (p = 0.07) of GC patients." (PMID 39796161, 2025). "A decreased ARID1A expression was already reported in GC tumor tissues, and it also was not statistically significant compared to the adjacent non-tumor tissue." (PMID 39796161, 2025). "In our study, ARID1A expression was significantly lower in tumor and adjacent non-tumor tissues compared to sectional normal gastric samples (p < 0.0001)." (PMID 39796161, 2025). "Ongoing research focusing on ARID1A and PI3K/AKT for the treatment of TNBC, by restoring ARID1A expression and inhibiting PI3K/AKT signaling, could successfully reduce tumor aggressiveness and improve the clinical outcomes in TNBC." (PMID 41514650, 2025). "In addition, ARID1A interacts with enhancer of zeste 2 polycomb repressive complex 2 subunit (EZH2) and thus influences the expression of a range of tumor-related molecules." (PMID 39773749, 2025). "When evaluating the potential regulatory pair ARID1A/miR-3613-3p, we also found a statistically significant weak negative correlation between expression in tumor r = −0.26 (p = 0.008) and in non-tumor tissues r = −0.25 (p = 0.009)." (PMID 39796161, 2025). "Genes associated with allograft rejection were upregulated in T24 and JMSU‐1 tumor cells but downregulated in both normal‐like models in the absence of ARID1A." (PMID 40170512, 2025). "ARID1A low expression is also shown to increase the number of myeloid-derived suppressor cells (MDSCs) via an increased activation of the NF-κB signaling pathway to produce more CXCL2 and CXCL3 chemokines to recruit MDSCs to the tumor microenvironment." (PMID 40429787, 2025). "Abnormal expression and variation of ARID1A and SMARCA4 in tumor drug resistance." (PMID 39697230, 2024). "Additionally, other studies have demonstrated that ARID1A inhibition induces epithelial–mesenchymal transition (EMT) and promotes tumor cell metastasis." (PMID 38893181, 2024). "Moreover, several epigenetic-related genes such as ARID1A, EP300, and CREBBP were also identified, highlighting the functional role of epigenetic modulation during tumor progression." (PMID 39334392, 2024). "Further, by assessing changes in histone modifications in the CDKN1A promoter region, which regulates the E2F1 transcription factor, we determined that ARID1A deletion downregulates CDKN1A acetylation, diminishes P21 protein transcription, and initiates a cascade of tumor drug resistance responses." (PMID 38600891, 2024). "AT-rich interaction domain 1A (ARID1A), a novel tumor suppressor gene, is a part of the multiprotein SWI/SNF chromatin remodeling complex and plays an important role in inhibiting the proliferation, differentiation, and invasion of tumor cells." (PMID 39619442, 2024).
tumor (continued). "In line with this, it has been reported that tumors lacking ARID1A expression exhibit higher tumor-infiltrating lymphocytes (TILs) and enhanced immune checkpoints, which render these tumors sensitive to immune checkpoint blockade therapy." (PMID 38587186, 2024). "In conclusion, ARID1A is an essential component of the SWI/SNF chromatin remodeling complex and a tumor suppressor mutated or absent in many tumors." (PMID 39697230, 2024). "ARID1A serves as a critical interface between EWS::FLI1 and the BAF complex, with its condensate-forming ability essential for the aberrant gene expression that drives tumor growth." (PMID 39344201, 2024). "In vivo tumor sensitivity to HHT inversely correlated with ARID1A levels suggesting that in the absence of ARID1A, pharmacological targeting of translational elongation can be utilized to restore its tumor suppressive properties." (PMID 37743426, 2023). "Previous research showed that the tumor mutational burden (TMB) of patients with ARID1A alterations was significantly higher than in those without, and cancers with multiple ARID1A alterations had the highest TMB level." (PMID 37711591, 2023). "After PSM and exclusion of spots without tumor tissue or detached from the slides, 107 ARID1A positive patients and 128 ARID1A negative patients were included in the mIF study." (PMID 37366273, 2023). "These discoveries indicate that the lack of ARID1A encourages tumour advancement in GC cells with the MSI‐H phenotype." (PMID 38041544, 2023). "For example, the MAPK1 copy number increased in the tumor from the secondary surgery while no change was observed in the first surgery, and ARID1A deletion was detected in the samples from the secondary surgery rather than that from the first surgery." (PMID 36982170, 2023). "Importantly, combination of ARID1A and CXCL13 in baseline tumor tissues suggested improved overall survival compared to either single biomarker." (PMID 36980292, 2023). "In this study, we found that ARID1A competitively binds to YAP to inhibit the production of the YAP/TEAD complex, leading to the suppression of its transcriptional activity and the consequent inhibition of tumour metastasis." (PMID 37173914, 2023). "Importantly, ARID1A-inactivated cells are more sensitive to treatment with Compound C, an AMPK inhibitor, as shown by a prolonged survival of tumor bearing mice." (PMID 36980292, 2023). "Additionally, when ARID1A KO ES2 tumors were treated with ERKi (cohort: ES2 AKO ERKi), a similar reduction in tumor growth was observed compared to the untreated cohort (ES2 AKO UT)." (PMID 38071325, 2023). "In conclusion, ARID1A and YAP co-regulate tumour metastasis in vivo." (PMID 37173914, 2023). "For example, E‐cadherin expression was downregulated or absent when ARID1A was silenced, and the loss of E‐cadherin led to epithelial‐mesenchymal transition (EMT), further increasing tumor aggressiveness." (PMID 37366273, 2023). "The absence of tumour suppressor factors such as ARID1A can create specific weaknesses in cancer cells that can be potentially targeted for treatment." (PMID 38041544, 2023).